SNORD36B (small nucleolar RNA, C/D box 36B)
Synonyms: U36b; RNU36B
Gene: Small nucleolar RNA gene on chromosome 9 (133,350,095 to 133,350,168, forward strand). Ensembl gene ENSG00000200831.
Gene Ontology:
Biological process: RNA processing
Cellular component: nucleolus
Homologues: Orthologues: chimpanzee SNORD36 (97% identical), macaque SNORD36 (95% identical), rat LOC120101983 (82% identical), mouse Gm22879 (81% identical), pig SNORD36 (81% identical), dog SNORD36B (76% identical), zebrafish SNORD36 (74% identical), rat LOC120101211 (73% identical), tropical clawed frog SNORD36 (73% identical). Paralogues in human: SNORD36A (69% identical), SNORD36 (55% identical), SNORD36C (51% identical).